AXIN1 (axin 1)
Diseases named in the same sentence as AXIN1 in open-access papers (continued):
Sharing a sentence is not in itself a finding about the gene and the disease.
infection (9 papers, 2011 to 2025). The state of being infected such as from the introduction of a foreign agent such as serum, vaccine, antigenic substance or organism. "Here, we found that Axin1 protein was significantly reduced by pathogenic Salmonella 8 hours postinfection, the early stage of infection in vivo." (PMID 22509369, 2012). "The Axin1 conditional mutant mice are available now, we will focus on the physiological role of intestinal Axin in in vivo in anti-inflammation and anti-infection for future studies." (PMID 22509369, 2012). "Axin1 apparently has a preventive effect on bacterial invasiveness and inflammatory response during the early stages of infection." (PMID 22509369, 2012). "The protein expression of seven proteins (CD8A, ST1A1, AXIN1, FGF-5, MMP-10, HGF, SIRT2) was significantly decreased and the protein expression of two proteins (MMP-1, TNFRSF9) was significantly increased in caspase-1-deficient cells compared to Cas9 cells following HK1651 infection." (PMID 40137780, 2025). "The combination treatment with both TMAO and CFT073 had significant additive effects on the release of PD-L1 and STAMBP and synergistic effects on the release of CDCP1, uPA, AXIN1, MMP-10, and CD40 compared to CFT073 infection alone." (PMID 37111409, 2023). "Six out of eight proteins were significant in the longitudinal analysis for at least one effect (time [ITGB1BP2, AXIN1, MMP1, STAMBP] or condition [GH, ITGB1BP2, 4E-BP1]), suggesting their importance both during hospitalization and after infection." (PMID 36405747, 2022). "Starting at 24 h post infection, HCMV stabilized the expression of TNKS and reduced its PARsylation activity, resulting in accumulation of Axin1 and reduction in its PARsylation as well." (PMID 26729153, 2015). "Concentrating on the canonical GSK-3 pathway from the chicken whole genome array, we found a significant upregulation in the expression of Axin-1, GSK-3β, and β-catenin in the heterophils 30–60 min after infection with S. Enteritidis." (PMID 26664916, 2014). "The effect of XAV939 on β-catenin expression may be both time- and cell-dependent, since in HFFs, despite the accumulation of TNKS and Axin1, the expression of β-catenin was determined largely by infection and not by XAV939." (PMID 26729153, 2015).
cardiovascular diseases (2 papers, 2020 to 2021). "miR-3574 upregulation ameliorated IH-induced cardiomyocyte injury through regulating cell viability and apoptosis via Axin1, indicating that miR-3574 and Axin1 can serve as a potential novel and effective therapeutic strategy for OSA-related cardiovascular diseases." (PMID 33582657, 2021).
infectious disease (2 papers, 2012 to 2019). A disorder directly resulting from the presence and activity of a microbial, viral, or parasitic agent in humans. "The results suggest a distinct biological function of Axin1 and Axin2 in infectious disease and intestinal inflammation while they are functionally equivalent in developmental settings." (PMID 22509369, 2012). "Since AXIN1 analyses are not commonly used, we do not know whether other inflammatory and infectious diseases express higher levels of this protein." (PMID 30621017, 2019).
neurological diseases (2 papers, 2014 to 2022). "The recent discovery of de novo CNV deletions of Axin1 and exome variants of the Grin2C family member Grin2B associated with ASDs further exemplify the utility of the synapse analysis pipeline in the functional analysis of risk genes of neurological disorders." (PMID 24633176, 2014).
bacterial infection (1 paper, 2012). "It is still unknown how Axin1 may synergistically regulate multiple signaling pathways, thereby altering the host response to bacterial infection." (PMID 22509369, 2012).
gastrointestinal tract cancer (1 paper, 2020).
immune diseases (1 paper, 2023). "Explorations in the role of myeloid Axin1 can potentially expound the tissue-specific function of Axin1 in auto-immune diseases." (PMID 38010886, 2023).
kidney disease (1 paper, 2024). "We also found, using the Olink proteomic platform, that TNF-α and TMAO enhanced the secretion of additional inflammatory-and growth mediators associated with kidney disease; VEGFA, GDNF, CDCP1, OPG, uPA, AXIN1, MMP-1, MMP-10, PD-L1, HGF, Flt3L, 4E-BP1, CD40, CASP-8, ADA, TNFRSF9, TWEAK44–61." (PMID 38643262, 2024).
AXIN1 also shares sentences with these, for which no sentence is quoted: glioma (5 papers); Familial adenomatous polyposis (3); leukemia (3); adenocarcinoma (2); endometrial cancer (2); endometrioid ovarian cancer (2); influenza (2); T-cell lymphomas (2); alcoholism (1); ameloblastoma (1); atrial septal defect (1); autoimmune disorders (1); benign teratoma (1); Bicuspid aortic valve (1); brain cancer (1); cleft palate (1); colonic adenoma (1); colorectal adenoma (1); craniofacial microsomia (1); depression (1); dilated cardiomyopathy (1); embryonal tumors (1); embryonic carcinoma (1); Epstein-Barr virus infection (1); esophageal cancer (1); Fanconi Anemia Complementation Group E (1); fibrosarcoma (1); gallbladder cancer (1); gastric adenocarcinoma (1); generalized anxiety disorder (1).
A further 28 diseases each share a sentence with AXIN1 in 1 paper.